KRAS (KRas proto-oncogene, GTPase)
Diseases named in the same sentence as KRAS in open-access papers (continued):
Sharing a sentence is not in itself a finding about the gene and the disease.
lung cancer (continued). "In the past, most studies that analyse KRAS-mediated effects focus on pancreatic and lung cancers." (PMID 33116132, 2020). "In the case of lung cancer, although all induced mostly by smoking, KRAS mutation is specific to adenocarcinoma but absent in small cell lung cancer." (PMID 32725342, 2020). "However, the development of targeted therapies for KRAS-mutant lung cancers has long been marked by frustration." (PMID 32548736, 2020). "Most strikingly, treatment data on cell line, xenograft tumor, and autochthonous lung cancer in transgenic mouse models showed that combinational inhibition of TAK1 and MEK1/2 effectively shrank lung cancer concurrently positive for KRAS mutation and CLU deficiency." (PMID 33052230, 2020). "Here we perform a genome-scale analysis using KRAS-mutant human pancreatic and lung cancer cell lines to investigate whether knock-down or overexpression of mutant KRAS as well as pharmacological inhibtion of ERK correlates with differential DNA methylation." (PMID 32576853, 2020). "Consistently, FASN inhibition blocks cellular proliferation of KRAS-driven lung cancer cells." (PMID 33194642, 2020). "Although oncogenic KRAS could serve as an excellent drug target opportunity owing to its high incidence in lung cancer, its direct inhibition has proven to be challenging owing to a lack of traditional small molecule binding pockets on the protein." (PMID 32365867, 2020). "In addition, silencing of pyruvate kinase isoenzyme M2 enhanced the efficacy of docetaxel and cisplatin (an alkylating agent) in human KRAS mutant lung cancer xenograft models." (PMID 32560574, 2020). "To summarize, although KRAS mutations represent one of the most common oncogenic driver mutations in lung cancer, KRAS has been historically acknowledged a non-druggable target." (PMID 32548736, 2020). "This work has culminated in a phase I trial of lead compound AMG 510 (NCT03600883) which produced partial responses in 50% of evaluable patients with KRAS G12C-mutant non–small cell lung cancer, and stable disease in the majority of patients with colorectal or appendiceal cancer." (PMID 31636382, 2020). "KRAS-4B is the dominant isoform in human cancers, and it is present in approximately 90% of pancreatic cancers, 30% to 40% of colon cancers, and 15% to 20% of lung cancers, mostly NSCLC." (PMID 32629823, 2020). "Moreover, Kirsten sarcoma viral oncogene homolog (KRAS)-mutant Calu-1 lung cancer cells exhibited higher sensitivity to erastin and silencing of KRAS by small hairpin (sh) RNA reduced erastin’s efficacy in these cells." (PMID 31936571, 2020). "Unlike the previous marker, KRAS is associated with tobacco use, with only 5 to 10% of KRAS-mutant lung cancers arising in never or light smokers." (PMID 32107398, 2020). "EGFR-mutated lung cancers are especially relevant, as EGFR activation can activate RAS signaling, and patients with EGFR mutations may have a concomitant gain-of-function KRAS mutation." (PMID 33335263, 2020). "A second study aims to test the safety of RO5126766 at different doses for patients with advanced KRAS+ lung cancer who have previously received treatment with a programmed cell death protein 1 (PD-1) or programmed cell death 1 ligand 1 (PD-L1) inhibitor (NCT03681483)." (PMID 32560574, 2020). "Interestingly, a recently published report claims that IKKα, the other catalytic subunit of the IKK complex, would be a better actionable target in KRAS-induced lung cancer, suggesting combined IKKα and IKKβ inhibition as a therapeutic approach." (PMID 32823550, 2020). "Therefore, patients with KRAS-mutant lung cancer often relapse indicating a substantial unmet medical need for these patients." (PMID 32913197, 2020).
lung cancer (continued). "In this regard, lung cancer investigations revealed that smoking could increase the EGFR and its downstream elements, such as KRAS and BRAF mutations." (PMID 33127962, 2020). "In addition, KP-LC VIReST resulted in significantly enhanced IFNγ responses to all lung cancer cell lines and the KRAS epitope." (PMID 32903551, 2020). "Thus, NOX-derived ROS promote the formation Actin-rich protrusions of the plasma membrane and mitochondrial ROS support KRAS-induced anchorage-independent growth of murine lung cancer cells." (PMID 32825452, 2020). "Apart from the correlation between the lung cancer subtypes and GGO, reports also suggest that there can be potential relationship between the mutation profile of some key oncogenic drivers (such as EGFR and KRAS) and the occurrence of specific GGO subtype." (PMID 33352869, 2020). "For example, the mutation in the oncogene KRAS Q61H has been referenced in COSMIC database (COSM555) and is a hotspot known to be oncogenic and found in several other malignancies such as large intestine and lung carcinomas." (PMID 32083805, 2020). "Indeed, upon genetic ablation of the copper uptake transporter CTR1, a maneuver that lowers intracellular copper, autophagy is decreased in a mouse model of KRAS-driven lung cancer, paralleled by a sizeable reduction of tumorigenesis." (PMID 32420529, 2020). "Moreover, REG4 was also upregulated in KRAS-mutant lung carcinoma and thus, is a novel biomarker in the lung adenocarcinoma subtype." (PMID 33489872, 2020). "However, for KRAS-mutant lung cancer, the treatment options are still limited, and chemotherapies remain the first-line recommendation." (PMID 31612108, 2019). "In terms of the histological type, KRAS mutations are associated more with mucinous adenocarcinoma or lung cancer with goblet cell morphology than with nonmucinous adenocarcinoma." (PMID 31783917, 2019). "Notably, this collateral sensitivity induced by drug resistance is also applicable to KRAS-mutant lung cancer cells that have undergone intratumor heterogeneity under pathological circumstances." (PMID 31431614, 2019). "Interestingly, we found that FAM83A but not FAM83B was downregulated in tumors bearing KRAS mutations as the EGFR mutation, KRAS mutation, and ALK rearrangement are largely mutually exclusive events in lung cancer." (PMID 31242643, 2019). "Apparently, co-occurring alterations further increase the heterogeneous complexity, which may explain inconsistent outcomes of clinical trials with KRAS-mutant lung cancers." (PMID 31612108, 2019). "A previous study has reported that MYC, SUZ12, and KRAS are the biotargets of miR‐487b in cigarette smoke‐induced lung cancer, leading us to speculate that miR‐487b could also suppress CRC tumorigenesis by inhibiting these three genes." (PMID 30791232, 2019). "KRA-533 suppressed tumor growth in a dose-dependent manner in lung cancer mutant KRAS xenografts." (PMID 30971271, 2019). "The combination of SMAP therapy with a MEK inhibitor could overcome therapy resistance in multiple mouse models of KRAS mutant lung cancer." (PMID 31623614, 2019). "We showed that HSP90/AXL/eIF4E-regulated endoplasmic reticulum (ER) stress response, or the unfolded protein response (UPR), represents an acquired dependency and confers a selective vulnerability in drug-resistant KRAS-mutant lung cancer cells that drug-naïve parental cells lack." (PMID 31431614, 2019).
lung cancer (continued). "As MT KRAS is present in 41% of NSCLC patients, this newly discovered MT KRAS-induced phenotypic switching could have important therapeutic implications for lung cancer." (PMID 31635338, 2019). "Different KRAS mutations are also found in lung cancer, which do not have the same cellular activity." (PMID 31221963, 2019). "KRAS is a well-known oncogene that is commonly found in pancreatic, colon, and lung cancers." (PMID 31729414, 2019). "Indeed, a recent study showed an increase in FGFR signaling upon MEK inhibition in KRas-driven lung cancer." (PMID 31146385, 2019). "However, in vitro findings show that KRAS-driven lung cancer cells degrade less albumin than isogenic lines derived from the pancreas." (PMID 31803611, 2019). "This study found that the combination of AZ628 and BP-1-102 showed a strongly synergistic interaction in KRAS-mutant lung cancer cells compared with wild-type cancer cells, and KRAS-mutant lung cancer cells were more sensitive to this combination than AZ628 or BP-1-102 single." (PMID 31484165, 2019). "Furthermore, in the context of lung cancer the subtype of KRAS-induced tumors (i.e., adenocarcinoma vs squamous carcinoma) is regulated by activation of the NOTCH signaling pathway and expression of SOX2." (PMID 31399087, 2019). "In this review, we provide an update on the most recent advances in KRAS-mutant lung cancer, with a focus on mechanistic insights into tumor heterogeneity, the potential clinic implications and new therapies on horizons tailored for KRAS-mutant lung cancer." (PMID 31612108, 2019). "KRA-533 enhanced KRAS activity in most human lung cancer cell lines tested, except H292." (PMID 30971271, 2019). "Significant antitumor activity was obtained in mice bearing KRAS-mutant lung cancer xenografts." (PMID 31470511, 2019). "In KRAS driven lung cancer, response rates to anti-PD-1 therapy are approximately 20%." (PMID 31134065, 2019). "Another report showed that mutant KRAS could activate RASSF1A to downregulate YAP level in a lung cancer model." (PMID 30833665, 2019). "Using nanoliposomal delivery of KRAS-targeting siRNAs, KRAS mRNA expression could be dramatically reduced with subsequent decrease in tumor growth and metastatic potential in colon and lung cancer models." (PMID 31681559, 2019). "Most mutations detected in CSF samples could be found in FFPE samples except for ALK G689R in 2 individuals and KRAS Q61L in 1 individual, demonstrating that most tumors in the brain originated from the primary lung cancer." (PMID 30755180, 2019). "Development of a new class of anticancer agents that directly targets KRAS may provide a more attractive option for the treatment of KRAS-mutant lung cancer." (PMID 30971271, 2019). "It is also conceivable that HSP90/AXL/eIF4E signaling strength, ER stress magnitudes, and UPR status may stratify subsets of patients with KRAS-mutant lung cancer who likely benefit from the combination therapy." (PMID 31431614, 2019). "In this study, we uncovered that AXL/eIF4E-regulated UPR signaling network, with HSP90 at the helm of the regulatory hierarchy, is an acquired dependency of and confers a selective vulnerability in KRAS-mutant lung cancer cells resistant to chemo and anti-MEK cancer drugs." (PMID 31431614, 2019). "In contrast, the moderate level of WT KRAS activation induced by KRA-533 caused significantly less apoptosis and autophagic cell death in a lung cancer cell line without KRAS mutation (i.e. H292)." (PMID 30971271, 2019).
lung cancer (continued). "Kirsten rat sarcoma (KRAS) mutations occur in about 30% of lung adenocarcinomas, and unlike other common oncogenic drivers (such as epidermal growth factor receptor (EGFR) and anaplastic lymphoma kinase (ALK)), effective targeted therapeutic strategies for KRAS mutant lung cancer have been limited." (PMID 30986992, 2019). "This study provided the mechanistic support for combinatorial treatment (MEK plus histone deacetylase inhibitors) for KRAS-mutant lung cancer, and, again, highlighted the importance of stratification of epithelial and mesenchymal subsets in decision-making for treating KRAS-mutant lung cancer." (PMID 31612108, 2019). "Development of this KRAS agonist may offer an effective approach for the treatment of mutant KRAS lung cancer." (PMID 30971271, 2019). "To explore the mechanism by which MYC overexpression in cancer cells correlates with proscillaridin A sensitivity, we compared its effects between MYC driven leukemic cells (MOLT-4 and NALM-6) and low expressing MYC cancers driven by KRAS mutations (SW48 colon and A549 lung cancer cells)." (PMID 31196146, 2019). "Notably, the unique dependency and sensitivity induced by drug resistance are applicable to KRAS-mutant lung cancer cells undergoing de novo intratumor heterogeneity." (PMID 31431614, 2019). "Instead, quantification of exoRNA (KRAS mutant) might be of high interest as it was recently reported for detecting mutant EGFR in lung cancer." (PMID 31717747, 2019). "KRAS mutations constitutively activate KRAS and subsequently its downstream Raf/MEK/ERK1/2 and PI3K/PIP3/AKT survival pathways in various cancers, including lung cancer." (PMID 30971271, 2019). "Also in lung cancer, the induction of mitosis seems to depend on activation of KRAS and CK1α phosphorylation of FADD during G2–M, where FADD interacted with G2–M cell-cycle regulatory components PLK1, AURKA, and BUB1." (PMID 31569512, 2019). "Mechanistically, acquisition of drug resistance enables KRAS-mutant lung cancer cells to bypass canonical KRAS effectors but entail hyperactive AXL/eIF4E, increased protein turnover in the ER, and adaptive activation of an ER stress-relief UPR survival pathway whose integrity is maintained by HSP90." (PMID 31431614, 2019). "Another compound targeting the KRAS G12C variant, ARS-853, selectively reduced the frequency of the active, GTP-bound KRAS, and inhibited cell proliferation in lung cancer models and suggests that nucleotide cycling between GDP and GTP bound forms are essential for its molecular functions." (PMID 31681559, 2019). "Given the presence of a variety of potent and specific chemicals, treating KRAS-mutant lung cancer remains a significant challenge, implying that the problem might be mechanism-related rather than the efficacy of targeting itself." (PMID 31612108, 2019). "It is known that Kirsten rat sarcoma viral oncogene homolog (KRAS) mutation is one of the most common genetic alterations involved in lung cancer and is associated with reduced response to IGF1R-targeted therapy in lung cancer cells." (PMID 29455661, 2018). "Treatment of NSCLC and other lung cancer cell lines with and without KRAS mutations at concentrations as high as 25 μM had no impact on proliferation." (PMID 29856759, 2018). "We further show here that high GATAD2B expression correlates with worsened outcomes in lung cancer patients and cooperates with KRAS to promote gain-of-function pro-oncogenic and pro-metastatic transcriptional programs including MYC to mediate cell invasion in vitro and tumor progression in vivo." (PMID 30013058, 2018). "Further, people who have never smoked are more likely to have KRAS p.G12D mutations in their lung cancers than are people who have smoked." (PMID 30412573, 2018). "It was also revealed that B7-H3-expressing cancers harbor KRAS mutations significantly more frequently, which may make a breakthrough in the treatment of KRAS mutant lung cancers." (PMID 30513627, 2018).
lung cancer (continued). "KRAS mutant A549 and H1944 lung cancer cells were exposed to GSK126 or vehicle in vitro." (PMID 30487290, 2018). "We tested 11 lung cancer cell lines - 8 with a KRAS or EGFR mutation and 3 with no known activating mutations in these genes – with a dosing strategy covering the previously determined active range of the drug." (PMID 30475204, 2018). "However, a vaccine comprised of multiple immunogenic peptides derived from KRAS showed promising activity in a mouse model of lung cancer, and it will be of great interest to follow the development of such lines of research." (PMID 29945886, 2018). "The ATF4 modulation exerted by oncogenic KRAS is required for apoptosis suppression via control of asparaginase biosynthesis: inhibition of AKT suppresses asparaginase expression and, combined with low extracellular asparagine, decreased the growth of KRAS-mutant lung cancers." (PMID 30060526, 2018). "Importantly, this model benefits from sporadic KRAS mutant expression leading to scattered tumor nodule formation and expansion, which resembles the human adenocarcinoma lung cancer type." (PMID 30220105, 2018). "Many factors may contribute to the heterogeneity of KRAS-mutant mouse lung cancer models, but a predominant role is played by the acquisition of cooperating genetic alterations spontaneously acquired during tumor development." (PMID 30060526, 2018). "KRAS-driven lung cancers represent an aggressive form of NSCLC." (PMID 30013058, 2018). "Both miRNAs were substantially increased in the lungs of mice treated with AdenoCre, suggesting that KRAS may exert its tumorigenic function through these two miRNAs at very early stages of lung cancer." (PMID 29440633, 2018). "The CRISP technology allowed to identify genes that act as tumor suppressors and may inhibit the KRAS-driven lung cancer development." (PMID 30060526, 2018). "Studies performed by 3V- Biosciences have shown an association of FASN inhibitor sensitivity with KRAS mutation status in lung cancer cell lines, but not in analysis of 29 CRC cell lines." (PMID 29872506, 2018). "Importantly, this drug combination induced regression of tumors in a KRAS-driven lung cancer mouse model." (PMID 30060526, 2018). "In a murine lung carcinoma model with mutated KRAS, it has been observed that the DLK1-DIO3 miRNAs cluster on chromosome on 12qF1 was substantially overexpressed, suggesting a role as an oncogenic driver of lung cancer in these circumstances." (PMID 29435111, 2018). "In NSCLC, co-occurrence of mutant KRAS and LKB1 loss has been shown to impact on the urea cycle enzyme CPS1 providing an alternative pool of carbamoyl phosphate to maintain pyrimidine availability thus imposing a growth advantage on lung cancer cells." (PMID 30514331, 2018). "However, in some lung cancer models that harbor KRAS mutations, CRAF is mediating oncogenic signaling from KRAS, suggesting it would be a target for pharmacological inhibition." (PMID 29455659, 2018). "Therefore we have investigated the efficacy of deltarasin in killing KRAS-dependent lung cancer cell lines and the role of autophagy and ROS generation in the cells’ response to deltarasin treatment." (PMID 29440631, 2018). "Effective therapies including standard chemotherapy to target lung cancer with mutated KRAS have not yet been developed." (PMID 28786996, 2017). "Thus, miR-29b is an important mediator of KRAS-dependent TSG silencing in human basal/secretory lung cancer." (PMID 29088821, 2017).